RN7SL251P (RNA, 7SL, cytoplasmic 251, pseudogene)
Gene: Miscellaneous RNA gene on chromosome 2 (85,442,495 to 85,442,791, forward strand). Ensembl gene ENSG00000244399.
Homologues: Orthologues: chimpanzee Metazoa_SRP (99% identical), macaque Metazoa_SRP (95% identical). Paralogues in human: RN7SL1 (82% identical), RN7SL2 (82% identical), RN7SL3 (81% identical), RN7SL45P (81% identical), RN7SL566P (81% identical), RN7SL113P (80% identical), RN7SL126P (80% identical), RN7SL220P (80% identical), RN7SL49P (79% identical), RN7SL788P (79% identical), RN7SL127P (79% identical), RN7SL478P (79% identical), and 700 more.